INSL3 (insulin like 3)
Diseases named in the same sentence as INSL3 in open-access papers (continued):
Sharing a sentence is not in itself a finding about the gene and the disease.
tumor (12 papers, 2012 to 2025). "Drosophila Dilp8, the mammalian homolog of INSL3, is released from tumor tissues and systemically controls the expression of feeding-associated neuropeptides through the Lgr3/Lgr8 receptor in the brain." (PMID 35388147, 2022). "First, DN was a highly heterogeneous tumor; thus, to evaluate the unique roles of INSL3 in different DN subtypes were necessary." (PMID 34233048, 2021). "The INSL3 protein is produced mainly in gonadal tissues in the human body; however, it has been identified in tumor tissues of the gastrointestinal tract." (PMID 23028900, 2012). "Circulating INSL3 concentration pre- and postpancreatic tumor resection." (PMID 40937417, 2025). "Adult Inha KO mice have reduced Leydig cell numbers; this is supported by RNAseq data showing an approximately 5-fold reduction in Leydig cell transcripts (Insl3, Klk1b21) in Inha KO ‘normal’ tubules, TAT tubules and tumours." (PMID 37564373, 2023). "Our present study shows that INSL3 peptide is not significantly produced by the tumor cells themselves or by any cells within PDAC tissue, and thus cannot be involved in a mechanism to induce cachexia." (PMID 40937417, 2025). "In C26 tumor-bearing mice, anorexia induced by INSL3 secretion started on Day 11, although no body weight changes were observed in this time period." (PMID 35388147, 2022). "Bilateralism of the tumours, presence of Reinke crystals and expressions of synaptophysin, Inhibin α, CD56, androgen receptor, DLK1, INSL3, CYP11B1, CYP21A2 and MC2R have all been studied as potential markers, but none of these markers individually can reliably discriminate TARTs from LCTs." (PMID 29038332, 2017).
bone disorder (1 paper, 2025). "However, INSL3 reduced sclerostin expression, further implicating INSL3 in KS-associated bone disorders." (PMID 40314150, 2025).
infection (1 paper, 2006). The state of being infected such as from the introduction of a foreign agent such as serum, vaccine, antigenic substance or organism. "However, infection of theca cells with the AF-1 activating function mutant unable to be phosphorylated by MAP kinases consistently led to a higher induction of CYP11A1, STAR, and INSL3 transcription." (PMID 17176485, 2006).
INSL3 also shares sentences with these, for which no sentence is quoted: Osteopenia (3 papers); abdominal hernia (2); Azoospermia (2); Insulin resistance (2); Ovarian Insufficiency (2); sarcopenia (2); adrenal rest tumor (1); breast adenocarcinoma (1); cardiovascular disease (1); Cirrhosis (1); congenital hypogonadotropic hypogonadism (1); Cutaneous T-Cell Lymphoma (1); endocrine disorders (1); endometriosis (1); endometritis (1); hematological diseases (1); infectious disease (1); kidney adenocarcinoma (1); male fertility (1); Micropenis (1); Oligomenorrhea (1); persistent Müllerian duct syndrome (1); premature ovarian failure (1); Sézary syndrome (1); testicular tumors (1); testis (1); type 2 diabetes mellitus (1); uterine disease (1).